RN7SL240P (RNA, 7SL, cytoplasmic 240, pseudogene)
Gene: Miscellaneous RNA gene on chromosome 11 (29,721,399 to 29,721,684, reverse strand). Ensembl gene ENSG00000243505.
Homologues: Orthologues: chimpanzee Metazoa_SRP (88% identical), macaque Metazoa_SRP (85% identical), dog Metazoa_SRP (66% identical), mouse Gm24812 (63% identical), rat Metazoa_SRP (63% identical), rabbit Metazoa_SRP (62% identical), dog Metazoa_SRP (58% identical), mouse Gm25687 (54% identical). Paralogues in human: RN7SL2 (70% identical), RN7SL1 (69% identical), RN7SL3 (68% identical), RN7SL617P (68% identical), RN7SL5P (67% identical), RN7SL242P (67% identical), RN7SL33P (67% identical), RN7SL4P (67% identical), RN7SL444P (66% identical), RN7SL278P (66% identical), RN7SL45P (66% identical), RN7SL769P (66% identical), and 703 more.